CD34 (CD34 molecule)
Diseases named in the same sentence as CD34 in open-access papers (continued):
Sharing a sentence is not in itself a finding about the gene and the disease.
Stroke (continued). "To determine translational significance of these changes and prove EPCs as juvenile protective factors, we tested whether infusing juvenile cd45- [cd34+/kdr+]EPCs can delay stroke onset in spTg25+ female rats, known to be the more susceptible to ischemic-hemorrhagic strokes than male rats." (PMID 23383116, 2013). "Despite varying results in the immunofluorescence analyses, IC, IA, and IN cell-treated stroke animals all displayed co-localization of CD34 with DCX and Iba-1, and CD34 was observed to be neighboring VEGFr1 markers in positive cells." (PMID 38016184, 2024). "The efficacy of CD34+ cells has also been investigated in the setting of neonatal brain injury, specifically using the MCAO model of stroke, and the Rice–Vannucci model of hypoxic-ischemic (HI) brain injury." (PMID 39075614, 2024). "Many studies have shown G-CSF mobilises CD34 + and CD133 + cells and clinical trials have investigated its therapeutic use in diseases such as cancer, stroke and liver failure, with mixed results." (PMID 39186241, 2024). "According to the first report of using autologous G-CSF mobilized CD34+ therapy in acute ischemic stroke patients, CD34+ cells improved modified rankin score (MRS) and national institutes of health stroke score (NIHSS) in the 6-month follow-up." (PMID 37138792, 2023). "Close correlation between baseline CD34 + KDR + and CD133 + KDR + counts and the outcome of stroke proposes these particular EPC subtypes as potential prognostic markers for ischaemic stroke." (PMID 38071215, 2023). "Association of NIHSS, mRS and BI scores at D90 to the numbers of circulating EPC subtypes pinpointed substantial correlations between decreased BL numbers of CD34 + KDR + and stroke severity on D90 (NIHSS: r: − 0.281; p: 0.043; mRS: − 0.343; p: 0.01)." (PMID 38071215, 2023). "In contrast, only reductions in D30 CD133 + KDR + (r: − 0.397; p: 0.006) and CD34 + CD133 + KDR + (r: − 0.399; p: 0.005) cell numbers were correlated with stroke severity on D90." (PMID 38071215, 2023). "We found that around 14 days post-stroke, significant angiogenesis occurs in the ischemic core, as determined by the presence of CD31+/CD34+ double-positive endothelial cells." (PMID 35626695, 2022). "Using flow cytometry and double labeling with CD34 and Flk-1, we confirmed a mobilized release of bone marrow ESCs/EPCs into the peripheral blood after 6-day PTH treatment in stroke mice." (PMID 24503654, 2014). "Stroke mice that received PTH treatment showed a marked increase, i.e. more than double the amount in controls, of CD34+/Flk1+ cells in peripheral blood (P<0.05)." (PMID 24503654, 2014). "Three EPC phenotypes were assessed by flow cytometry at 48 hours after stroke: a) CD31/CD34, b) CD62E/CD34, and c) KDR/CD34." (PMID 20003528, 2009). "Our results revealed that post-stroke EE treatment promoted functional recovery in a pro-angiogenesis manner through astrocytic IL-17A, which might promote CD34 and VEGF expression during the recovery phase of stroke." (PMID 36873773, 2023). "Endothelial progenitor cells (EPCs), expressing markers for stemness (CD34), immaturity (CD133) and endothelial maturity (KDR), may determine the extent of post-stroke vascular repair." (PMID 38071215, 2023). "Immunohistochemistry revealed EPC activation and localization and enhanced vascularization in G-CSF-treated animals, as demonstrated by increased levels of EPC and vasculogenesis markers, CD34+ and VEGFR-2 and vWF, respectively, in the ipsilateral cortex and striatum of stroke animals." (PMID 29857523, 2018). "A ROC-curve analysis showed that CD56+/CD34+/AV+ cMPs at a cut-off point of 2.8 cMPs/μl of PFP, P<0.0001, properly discriminated between controls and stroke patients with a 81.8% sensitivity and 83.3% specificity [area under de curve (AUC) = 0.894 (95% CI 0.823, 0.965)]." (PMID 26815842, 2016).
Stroke (continued). "In vivo EPC infusion of male, juvenile non-expanded cd45-[cd34+/kdr+] EPCs into female stroke-prone rats prior to stroke attenuated progression and delayed stroke onset (P<0.003)." (PMID 23383116, 2013). "Although previous clinical data have demonstrated a positive benefit in patients with stroke, there are no clinical reports on autologous CD34 positive precursor cells in the treatment of poststroke." (PMID 24187628, 2013). "In conclusion, this study indicates that intrathecal administration of CD34 positive cells in patients with past stroke is a relatively safe and simple procedure with no long-term adverse effects." (PMID 24187628, 2013). "After stroke, SVCT2 was localized specifically in brain capillary endothelial cells immunoreactive for the tight junction marker Occludin and the endothelial cell markers VWF and CD34." (PMID 21347255, 2011). "Additionally, we previously demonstrated that UCB-derived CD34+ cells, but not mature cells, have a therapeutic effect on experimental stroke in mice." (PMID 38519559, 2024). "EPC subsets in the stroke population were quantified at day 1, as follows: 0.02% (0.01-0.04) CD133+CD34+, 0.01% (0.001-0.02) CD133+VEGFR2+, 0.002% (0.0006-0.004) CD34+VEGFR2+ and 0.0009% (0.0003-0.0018) CD34+CD133+VEGFR2+ (medians and first and third quartile)." (PMID 21871109, 2011).
acute lymphoblastic leukemia (50 papers, 2010 to 2026). Leukemia with an acute onset, characterized by the presence of lymphoblasts in the bone marrow and the peripheral blood. "Notably, CD34 is a surface protein commonly associated with HSCs and is used as a marker in various leukemia types, including acute lymphoblastic leukemia (ALL) and AML." (PMID 39830209, 2024). "This study reports that a leukemic cell immunophenotype with high CD34 surface expression predicts poor induction therapy response in B‐cell precursor acute lymphoblastic leukemia." (PMID 35271751, 2022). "CD10 and CD34 are surface markers that have been reported to have prognostic relevance in childhood lymphoblastic leukemia, but the results were conflicting." (PMID 35178316, 2022). "2020Generation of an induced pluripotent stem cell line KUMCi001-A from CD34+ bone marrow cells of a patient with acute lymphoblastic leukemia using human placenta-derived cell conditioned mediumStem Cell Research: Lab resourceIn Press." (PMID 32904343, 2020). "Almost all human and canine CLL have been reported as CD34−, while acute lymphoblastic leukemia (ALL) may exhibit concurrent CD34 expression; therefore, CD34 expression serves as a useful marker for distinguishing CLL from ALL." (PMID 39462364, 2024). "Moreover, ITGA6 expression is substantially more common in CD34+ pre-B-acute lymphoblastic leukemia than in CD34- pre-B-acute lymphoblastic leukemia." (PMID 37444576, 2023). "Therefore, we aimed to evaluate sGRP78 in pediatric patients with B-lineage acute lymphoblastic leukemia (B-ALL) at diagnosis and investigate its association with stem cell markers (CD34 and CD38), lineage markers (CD10 and CD19)." (PMID 35149705, 2022). "HPCs are able to sense a gradient of SCF as revealed from studies by Colmore and colleagues using a severe combined immunodeficiency mouse xenograft model of human HPCs (CD34+ve cells from cord and peripheral blood) and Nalm-6 pre-B acute lymphoblastic leukemia cells." (PMID 32235353, 2020). "Acute lymphoblastic leukemia (ALL) cases with high expression of CD34 exhibit worse outcome." (PMID 41296384, 2025). "Lymphoblast from both pediatric and adult B-acute lymphoblastic leukemias (B-ALL) show moderate to highly increased CCN2 mRNA expression compared with control cells (often CD34 positive cells, CD19+igM− cells or mononuclear cells) in the majority (60–80%) of cases." (PMID 33428075, 2021). "We therefore selected another patient (acute lymphoblastic leukemia; ALL) with a similar amount of confirmatory testing results and compared CD34+ cell viability after thawing." (PMID 31575081, 2019). "By co-culturing mesenchymal stem cells (MSC) with the REH acute lymphocytic leukemia (ALL) cell line, we have established an in vitro leukemic niche for the functional evaluation of hematopoietic stem/progenitor cells (HSPC, CD34+ cells)." (PMID 28216566, 2017). "For childhood pre-B acute lymphocytic leukemia, LIC were found in all maturation stages including CD34+ and CD34- populations." (PMID 24223100, 2013). "Although none of the PTCLs in this study expressed cell surface CD34 by flow cytometry, distinguishing them from T-cell acute lymphoblastic leukemia (T-ALL), several genes associated with immaturity or early T-cell development were upregulated in the transcriptome." (PMID 38166662, 2024). "In B-cell precursor acute lymphoblastic leukemia in children, the presence of CD34+CD38− lymphoblasts at the diagnosis does not affect the first remission of the disease." (PMID 37675394, 2023). "Rb is not phosphorylated on Ser608 residue and is tethered to nuclear structures in CD34+ hemopoietic progenitor cells, suggesting that it has growth-suppressive activity, whereas Rb(Ser608) is phosphorylated by CDK4/6 complexes in acute lymphoblastic leukemia cells." (PMID 31784636, 2019).
acute lymphoblastic leukemia (continued). "Flow cytometry confirmed precursor B-cell acute lymphoblastic leukemia (B-ALL), with the blasts expressing CD123, CD73/86, CD9, CD34, TdT, HLA-DR, CD58, CD38, cCD22, sCD22, cCD79a, and CD19, along with partial expression of CD24 and aberrant CD33." (PMID 40718322, 2025). "Our present study attempts to test for the sensitivity of the MRD “lite” panel using CD38, CD10, CD19, CD34, and CD45 for the diagnosis of residual disease in B-cell acute lymphoblastic leukemia (B-ALL)." (PMID 39634988, 2024). "For verification of the presence of (V)SLSLCs, we analyzed the levels of CD34, CD45, and CD2 markers in two Acute Lymphoblastic Leukemia (ALL) sub-types: Raji and Jurkat." (PMID 38067224, 2023). "In childhood acute lymphoblastic leukemia (ALL) for instance, this miRNA was found in samples positive for MLL translocations at levels 4 times greater when compared with normal CD34+ progenitor cells." (PMID 36553642, 2022). "In pediatric T cell acute lymphoblastic leukemia (T-ALL), serially transplantable LIC consisted of CD34+CD4− and CD34+CD7− fractions in newly diagnosed patient samples." (PMID 32796631, 2020). "FLAER binding was also lower in B-cell acute lymphoblastic leukemia (B-ALL) precursors (MFI = 3894.43) than in CD34+ and CD34− B-lymphoid precursors from control bone marrow (MFI = 11,235.60 and 17,448.67, respectively; Mann–Whitney U p < 0.005) (lymphoid component)." (PMID 39595968, 2024). "For example, CD34 was shown to be expressed in 24/45 of adult acute lymphoblastic leukemia (ALL) and was associated with Pgp-MDR1 phenotype and worse outcome compared with 21/45 CD34 negative cases." (PMID 32010428, 2020). "This study was aimed to dissect the prognostic significances of hematogones and CD34+ myeloblasts in bone marrow for adult B-cell acute lymphoblastic leukemia(ALL) without minimal residual disease(MRD) after the induction chemotherapy cycle." (PMID 31871314, 2019). "Additional markers, such as for B-cell precursor phenotype (TdT, CD34, and CD99) can help rule out an acute lymphoblastic leukemia." (PMID 29850589, 2018).
leiomyoma (49 papers, 2009 to 2026). A well-circumscribed benign smooth muscle neoplasm characterized by the presence of spindle cells with cigar-shaped nuclei, interlacing fascicles, and a whorled pattern. "GIST shows positive stains for CD 117, DOG-1, and CD 34, whereas leiomyoma expresses CD34, desmin, and SMA." (PMID 39027743, 2024). "The group also shows that WNT4 is overexpressed in CD34+/CD49b− leiomyoma cells and can stimulate leiomyoma cell proliferation via WNT/CTNNB1 signaling and AKT." (PMID 35203298, 2022). "It is important to differentiate angioleiomyoma from other types of spindle cell tumor, including leiomyoma (CD34- and S-100-), myopericytoma (desmin-, CD34-, and S100-), and myofibroma (desmin-, CD34-, and S-100-/+)." (PMID 30148476, 2018). "The positivity of CD34 helped us to exclude leiomyoma, leiomyosarcoma, fibromatosis, and fibrosarcoma." (PMID 24490095, 2013). "Spindle-shaped elements with elongated nuclei were appreciable; moreover, the cytoplasmatic immunohistochemical positivity for smooth muscle actin and desmin strongly supported the diagnosis of leiomyoma when also taking into account the constant negativity for CD34, CD117 and S100." (PMID 24959231, 2014). "Immunohistochemical staining can differentiate GISTs, which have c-kit mutations and are positive for CD117 and CD34 from leiomyomas, which are CD34 and CD117 negative, with no c-kit mutations." (PMID 23738186, 2013). "Most IFPs express CD34 and lack markers such as CD117 (c-KIT) and S100, assisting in their differentiation from GISTs, leiomyomas, and neural tumors." (PMID 40636665, 2025). "Leiomyomas that originate in the gastrointestinal tract or omentum positively express SMA and Desmin and negatively express ER, PR, CD117, Dog-1, CD34, and S100, and the tumors are all composed of smooth muscle cells without endometrial components." (PMID 36086793, 2022). "A total of eight leiomyoma-related DEGs (EGR1, CEBPB, IL6, PECAM1, VWF, TNFRSF1A, CD34 and ACE) were found upregulated in MF versus M only." (PMID 33807176, 2021). "Smooth muscle tumors such as leiomyoma and leiomyosarcomas show strong positivity for actin and desmin and negativity for S100, BCL2, and CD34." (PMID 34211794, 2021). "CD117 and CD34 are positive in GIST and muscle-specific proteins, such as actin, Desmin and caldesmon are positive in smooth muscle tumors such as leiomyoma and leiomyosarcoma." (PMID 30710876, 2019). "It is important to differentiate angioleiomyoma from other types of spindle cell tumor, including leiomyoma (CD34− and S-100−), myofibroma (desmin−, CD34− and S-100−/+) and myopericytoma (desmin−, CD34− and S100−)." (PMID 24959254, 2014). "This case was positive for CD34 and CD117, which supports the diagnosis, as this test distinguishes a GIST from mesenchymal tumors arising from smooth muscle cells, such as leiomyomas, leiomyoblastomas, and leiomyosarcomas." (PMID 23039908, 2012). "Immunohistochemistry was positive for desmin and α-smooth muscle actin (αSMA), partially positive for CD34, and negative for S100, confirming leiomyoma." (PMID 41940047, 2026). "Histopathology showed interlacing fascicles of bland spindle cells with cigar-shaped nuclei, positive for SMA and desmin and negative for S-100 and CD34, confirming leiomyoma." (PMID 41300875, 2025). "Edematous leiomyoma is often arranged in a nodular pattern and is surrounded by edematous connective tissues, with no CD34-positive blood vessels surrounding the tumor cells on immunohistochemistry." (PMID 40276735, 2025). "stromal tumors and leiomyomas of the gastrointestinal tract were expressed to have negative S-100, with stromal tumors expressing positive CD34, CD117, and Dog-1, with Dog-1 being the most sensitive and SMA and Desmin being positive in leiomyoma." (PMID 35538511, 2022). "Leiomyomas are usually positive for desmin, SMA, CD117, CD34 and DOG-1 at low levels." (PMID 28492717, 2017).
leiomyoma (continued). "The leiomyoma was immunohistochemically positive for vimentin, α-smooth muscle actin, and desmin (1 case), but negative for cytokeratins, CD34, KIT, and PDGFRA." (PMID 27956961, 2009). "Leiomyomas are presented typically globally positive for desmin and smooth muscle actin, while they are negative for CD34 and CD117 (c-kit)." (PMID 20030817, 2009). "The neoplastic cells of leiomyomas and leiomyosarcomas are strongly and diffusely positive for smooth muscle actin and desmin but negative for CD34 and CD117 while GISTs are strongly and diffusely positive for CD117, with a cytoplasmic, membranous, or paranuclear “dot-like” pattern." (PMID 31439993, 2019). "Conversely, leiomyoma accounts for desmin immunostaining and negative immunoreactivity for CD117 and CD34." (PMID 39994024, 2025). "Stains targeting smooth muscle-specific markers like SMA and desmin support their derivation from the smooth muscle, while CD34 and CD117 are negative in leiomyoma but positive in GIST." (PMID 39479071, 2024). "Smooth muscle differentiation in leiomyomas is confirmed by positive staining for smooth muscle actin (SMA), h-Caldesmon, HHF35 and desmin, while immunohistochemical staining for CD34 and S100 protein is negative." (PMID 36611301, 2022). "GISTs are positive for CD34, CD117, and DOG-1, while leiomyomas are negative with immunohistochemical staining." (PMID 34918628, 2021). "Leiomyomas are positive for SMA, desmin, and muscle-specific actin and negative for CD117 (c-kit), CD34, and S100 protein." (PMID 31610453, 2019). "In contrast to GIST, leiomyomas are uniformly negative for CD117 and CD34 and are positive for muscle markers including smooth muscle actin and desmin." (PMID 24991446, 2014). "In the other case, leiomyoma was suspected, but the possibility of the end of GIST could not be denied because of the presence of CD34‐positive cells." (PMID 37359151, 2024). "Leiomyomas usually stain positive for SMA and desmin but negative to CD117 and CD34." (PMID 34567524, 2021). "The primary diagnosis was cellular leiomyoma and now reviewed as GIST based on morphology and immunohistochemical staining results, which showed that the tumor cells were positive for CD117, but negative for CD34, a-SMA, desmin and S-100." (PMID 23902675, 2013). "Leiomyomas and leiomyosarcomas are differentiated from GISTs by positive immunoreactivity for desmin and smooth muscle actin and negative immunoreactivity for C-KIT (CD117) and CD34." (PMID 20307271, 2010).